RN7SL223P (RNA, 7SL, cytoplasmic 223, pseudogene)
Gene: Miscellaneous RNA gene on chromosome 11 (93,556,913 to 93,557,206, forward strand). Ensembl gene ENSG00000240202.
Homologues: Orthologues: chimpanzee Metazoa_SRP (98% identical), macaque Metazoa_SRP (89% identical). Paralogues in human: RN7SL1 (82% identical), RN7SL2 (82% identical), RN7SL3 (81% identical), RN7SL45P (81% identical), RN7SL126P (80% identical), RN7SL464P (80% identical), RN7SL709P (80% identical), RN7SL147P (79% identical), RN7SL311P (79% identical), RN7SL383P (79% identical), RN7SL597P (79% identical), RN7SL665P (79% identical), and 704 more.